MIR216A (microRNA 216a)
Synonyms: hsa-mir-216; hsa-mir-216a; MIR216; MIRN216; MIRN216A; miRNA216; mir-216; mir-216a
Gene: MicroRNA gene on chromosome 2 (55,988,950 to 55,989,059, reverse strand). Ensembl gene ENSG00000207798.
Gene Ontology:
Biological process: miRNA-mediated post-transcriptional gene silencing
Cellular component: RISC complex
Homologues: Orthologues: chimpanzee ptr-mir-216a (100% identical), macaque mml-mir-216a (97% identical), pig ssc-mir-216-1 (90% identical), dog MIR216A (89% identical), rat Mir216a (80% identical), tropical clawed frog xtr-mir-216 (71% identical), guinea pig MIR216A (63% identical), mouse Mir216a (60% identical). Paralogues in human: MIR216B (35% identical).
Diseases named in the same sentence as MIR216A in open-access papers:
MIR216A is named in the same sentence as 3 diseases in open-access papers, as found by Europe PMC text mining. Sharing a sentence is not in itself a finding about the gene and the disease. The quoted sentences say what the papers report.
glioma (1 paper, 2021). A benign or malignant brain and spinal cord tumor that arises from glial cells (astrocytes, oligodendrocytes, ependymal cells). "Similarly, MIR216A has been reported to manifest tumor suppressing properties in glioma cells, yet it is also found that its role has been contradictory, as it participates either as tumor suppressor or oncogene depending on the tumor type." (PMID 34204289, 2021).
CNS tumors (1 paper, 2021). "In our study, MIR216A was up-regulated in the majority of the examined CNS tumors, suggesting that it functions as an oncogene." (PMID 34204289, 2021).
MIR216A also shares sentences with these, for which no sentence is quoted: tumor (1 paper).